BDNF (brain derived neurotrophic factor)
Diseases named in the same sentence as BDNF in open-access papers (continued):
Sharing a sentence is not in itself a finding about the gene and the disease.
depression (continued). "When we compared BDNF methylation between individuals with chronic depression (n=185) and those free of depression (n=712), the same pattern of association was observed as previously." (PMID 26285129, 2015). "We have shown that late-life depression is associated with elevated BDNF methylation of specific CpG sites within promoters I and IV, with all associations remaining after adjustment for a range of covariates." (PMID 26285129, 2015). "Deficiency of the BDNF/CREB function made rodents susceptible to depression, while administration of BDNF/CREB produced antidepressant-like effects in models of depression." (PMID 25618406, 2015). "Multiple regression analysis adjusted for age, sex, body mass index, dose of antidepressant, and depression severity showed that TCI Self-Directedness (SD) scores were negatively associated with serum BDNF levels (β = −0.23, p = 0.026)." (PMID 25885038, 2015). "The present study examines the extent to which maternal early pregnancy serum BDNF levels are associated with antepartum depression." (PMID 25886523, 2015). "It was found that children carrying the BDNF Met allele, whose mothers suffered from depression, as well as children carrying the 5-HTTLPR S allele display a memory bias for negative self-descriptive traits." (PMID 26230319, 2015). "While the Val66Met polymorphism of BDNF is strongly associated with major depression, several independent studies and meta-analyses have reported that this polymorphism does not increase the risk for developing PD and severity of symptoms." (PMID 25806005, 2015). "Changes in pro-BDNF were also negatively associated with depression severity (Spearman's ρ=−0.253, P=0.013)." (PMID 26151924, 2015). "Previous studies have demonstrated lower serum BDNF levels in patients with major depressive disorder (MDD) and reported an association between BDNF levels and depression-related personality traits in healthy subjects." (PMID 25885038, 2015). "Our study is among the first to examine the potential effects of BDNF genotype on modifying the association between depression and BDNF methylation levels." (PMID 26285129, 2015). "BDNF, an important neurotrophic factor, has also been implicated in the etiology of major depression and the mechanism of antidepressant treatment." (PMID 26138544, 2015). "Lower levels of both serum and plasma BDNF are associated with major depressive disorder, and serum levels in particular have been correlated to severity of depression." (PMID 25908105, 2015). "Shame-proneness was also positively associated with subclinical depression and anxiety symptoms, and like guilt-proneness, this emotional disposition was affected by the BDNF Val66Met and early trauma interaction." (PMID 26230319, 2015). "For CpG analytical unit 7.8.9 of BDNF promoter I, a trend association of increased methylation with depression was observed as well as a modifying effect by two polymorphisms (P-values for interaction term: rs908867, P=0.046; rs962369, P=0.004)." (PMID 26285129, 2015). "Based on this study, adolescents with higher levels of childhood trauma and the BDNF low-expressing allele are primary candidates for prevention programs focused on anxiety and depression and other forms of psychopathology related to increased guilt." (PMID 26230319, 2015). "In unadjusted linear regression analysis, depression was associated with a significantly higher level of BDNF promoter I methylation at CpG unit 3.4.5, with an effect size (Δ mean methylation) of 0.4%, P=0.0002." (PMID 26285129, 2015). "Changes in serum BDNF and pro-BDNF levels at week 12 were inversely associated with depression severity." (PMID 26151924, 2015). "Previous studies have found associations between BDNF and depression, schizophrenia, and other mental illnesses." (PMID 26405456, 2015). "Among other genes, the brain-derived neurotrophic factor (BDNF) has been associated with major depression and with neuroticism." (PMID 26175754, 2015).
depression (continued). "The association between changes in serum BDNF levels and depression severity remained significant in the placebo group alone." (PMID 26151924, 2015). "Further, the evidence that episodes of depression are associated with low peripheral BDNF is mostly based on cross sectional data and studies following patients over time are mostly follow-up studies including an active medical treatment." (PMID 26011424, 2015). "Altered central and peripheral BDNF levels have been implicated in both depression and stress, both of which are risk factors for suicidal behaviour." (PMID 26718989, 2015). "BDNF is a neurotropic peptide essential for survival and proliferation of neurons in the brain, and low levels have been found among persons with depression, while use of antidepressant agents has been associated with upregulation of BDNF production." (PMID 26457080, 2015). "Depression and stress are associated with low levels of BDNF in the hippocampus and prefrontal cortex but high levels of BDNF in the amygdala and nucleus accumbens." (PMID 25908105, 2015). "After adjustment for age, sex and antidepressant use, methylation of CpG unit 3.4.5 in BDNF promoter I (β=0.094, s.e.=0.029 and P=0.001) and CpG 3 in promoter IV (β=0.31, s.e.=0.14 and P=0.025) remained significantly associated with depression." (PMID 26285129, 2015). "It is well known that BDNF mediated signaling pathways are implicated in the neuroplasticity alterations evoked by depression and antidepressants." (PMID 25821488, 2015). "A history of early trauma in adults carrying the BDNF Met allele is associated with reduced hippocampal gray matter and depression." (PMID 26230319, 2015). "Much of the research regarding a potential role for BDNF in the mechanisms underlying psychiatric disorders has been conducted in the context of animal-models of depressive disorders." (PMID 25932008, 2015). "As expected, it has been demonstrated that serum BDNF levels of women with postpartum affective disorders (depression, manic, and mixed episode) showing suicide risk are lower than those of women showing no risk." (PMID 25309465, 2014). "Several studies demonstrated an association between the serum BDNF levels and severity of major depressive disorder." (PMID 25538582, 2014). "Despite these limitations, our results provide evidence of an interaction between the BDNF met allele and early parenting on the development of depression/anxiety symptoms." (PMID 25425456, 2014). "Although not significant, it is interesting to note that the SNPs in the BDNF gene showed the strongest evidence of association with any mood disorder diagnosis, in comparison to specific diagnoses (bipolar disorder or major depressive disorder)." (PMID 24944871, 2014). "Researchers have found that the TRKB-independent pro-BDNF signaling pathway is the causative factor of compromised synapse, and potentially eliciting depression." (PMID 24632812, 2014). "Contradicting results show that, within the MTL, both increased and decreased regional brain volumes as well as BDNF levels were associated with severe depression and its treatment by ECT." (PMID 25505429, 2014). "The Met allele of the BDNF gene is associated with depression in the context of childhood adversity and genetic risk." (PMID 25425456, 2014). "A total of 22 studies with a pooled sample of 14,233 individuals were included in this review, of which 8 provided evidence in support of an interaction between life stress and the BDNF Val66Met polymorphism in depression." (PMID 24433458, 2014). "Our results provide evidence of an interaction between the BDNF met allele and early parenting on the development of depression/anxiety symptoms." (PMID 25425456, 2014). "Several studies have provided evidence that the 5-HTTLPR and BDNF Val66Met polymorphisms interact in predicting depression after ELS." (PMID 24596569, 2014).
depression (continued). "Previous studies have found an interaction between the BDNF Met allele and early adversity on the development of depression symptoms in adulthood." (PMID 25425456, 2014). "The BDNF G-712A polymorphism, a genetic variant located in the putative promoter region, has been reported to be associated with major depression in Chinese." (PMID 25383981, 2014). "Substantial evidence supports an association between depression and lower serum BDNF but evidence regarding correlations between BDNF and basic characteristics like sex, age, and BMI is equivocal." (PMID 24670553, 2014). "Subsequent research a decade later implicated VNS in upregulating gene expression of BDNF and fibroblast growth factor (bFGF) in the rat brain, suggesting a possible mechanism for the beneficial effects seen in the treatment of depression with VNS." (PMID 25009531, 2014). "The results of the meta-analysis showed that the effect of stressful life events on depression is significantly moderated by the BDNF polymorphism." (PMID 24433458, 2014). "Serum BDNF showed strong associations with race, platelet count, and depression after adjusting for other factors, and weak associations with a number of other participant characteristics." (PMID 24670553, 2014). "BDNF has been implicated in the pathogenesis of multiple neuropsychiatric diseases, including depression, schizophrenia, and Rett syndrome, a severe developmental disorder with autistic features." (PMID 24672476, 2014). "The most well-studied of these is BDNF, which has been linked to multiple neuropsychiatric diseases including bipolar disorder, depression, and schizophrenia." (PMID 24672476, 2014). "Although the findings were controversial, previous human studies of BDNF Val66Met polymorphism had reported that only BDNF Met/Met homozygosity was associated with heightened anxiety and an increased risk of depression." (PMID 25383981, 2014). "We found an association between serum BDNF and several characteristics that are also associated with dementia (race and depression), suggesting that future studies should control for these potential confounders." (PMID 24670553, 2014). "Combining the results from the identified studies with a total of 14,233 participants showed that the interaction between the Met variant of the BDNF Val66Met polymorphism significantly moderates the relationship between life stress and depression (P = 0.03)." (PMID 24433458, 2014). "Aside from the Val66Met allele of BDNF, the C allele of the SNP G11757C and the A allele of G196A were also more common in AD patients with depression." (PMID 25133184, 2014). "In conclusion, our study shows that LPS-induced inflammation caused depression-like behavior, as well as alterations in BDNF protein and spine density within the hippocampus, PFC, and NAc." (PMID 25628381, 2014). "The relationship between the Val66Met variant in the BDNF gene and stress in depression has been widely researched and thus a systematic review and meta-analysis is warranted to synthesise the literature." (PMID 24433458, 2014). "The results suggest that the Met allele of BDNF Val66Met significantly moderates the relationship between life stress and depression (P = 0.03)." (PMID 24433458, 2014). "The majority of published studies have focused BDNF Val66Met, which allows for the present meta-analysis, but it would be useful for future studies to explore the relationship between other BDNF polymorphisms and stress in depression." (PMID 24433458, 2014). "FD induced elevation of FKBP5 and suppression of BDNF, which are often linked with the improvement of anxiety disorder, depression, and post-traumatic stress disorder." (PMID 24632812, 2014). "Decreased BDNF signaling is associated with the pathophysiology of depression and the mechanisms underlying the actions of antidepressant drugs (AD)." (PMID 24817844, 2014).
depression (continued). "A meta-analysis provided evidence for an interaction between the Met variant of the BDNF Val66Met polymorphism and life stress in the causation of depression." (PMID 24433458, 2014). "Out of the 22 studies included, 8 reported a significant interaction between life stress (either life events or child adversity) and the Met variant of BDNF Val66Met in depression." (PMID 24433458, 2014). "Accumulating evidence has shown that BDNF was implicated in the pathophysiology of depression and the antidepressant action of exercise." (PMID 25477997, 2014). "It is possible that our estimate of the association between BDNF and depression was attenuated due to the mixture of treated and untreated individuals." (PMID 24670553, 2014). "It has been shown that the use of repetitive transcranial magnetic stimulation (rTMS) in depression can be linked to increased BDNF levels, and yet met carriers appear to be significantly less responsive to this procedure." (PMID 24999318, 2014). "According to previous cross-sectional studies, insulin sensitivity was associated with circulating BDNF, and hyperinsulinemia was a risk factor for depression." (PMID 24524285, 2014). "Post-mortem data from depressed patients showed that depression is associated with a decrease in BDNF levels in the hippocampus and PFC, and an increase of BDNF in the NAc." (PMID 25628381, 2014). "In animal models of depression, chromatin remodeling of brain-derived neurotrophic factor (BDNF) promoters leads to site-specific increased BDNF transcription, a change shown to mediate susceptibility to stress in humans and in mouse models." (PMID 23680237, 2013). "As compromised synaptic and structural plasticity is significantly associated with depression, the importance of BDNF in depression has therefore garnered considerable attention." (PMID 23847583, 2013). "In contrast to these findings, however, BDNF was less affected by early adversity in Met carriers, even though the Met allele was associated with increased depression susceptibility." (PMID 23824678, 2013). "In case of the genotypic association of BDNF, analyses using the recessive model showed association between the SNP and the risk of depression (χ2= 8.205,P= 0.004)." (PMID 24274373, 2013). "Evidence of an association between the BDNF Val66Met polymorphism and depression is rapidly being replicated." (PMID 24274373, 2013). "Depression has been strongly and consistently linked to low levels of BDNF, and it is thought that BDNF signaling mediates the hippocampal neurogenesis that has been linked to depression recovery." (PMID 23653854, 2013). "Apart from this, BDNF is the most prevalent growth factor in the central nervous system (CNS) and is widely implicated in psychiatric diseases, such as major depressive disorder (MDD), schizophrenia, addiction, and Rett syndrome." (PMID 23712361, 2013). "Brain-derived neurotrophic factor (BDNF) has been implicated in the etiology and treatment of depression." (PMID 23691371, 2013). "After adjustment for gender, HbA1c, BMI and numbers of complications, BDNF Val/Met genotype distributions (OR = 2.105, p < 0.05) and decreased serum BDNF levels (OR = 0.835, p < 0.01) were independently associated with depression in T2DM." (PMID 23968401, 2013). "Of particular import, research supports a biologic epistatic role of BDNF with 5-HTTLPR for the prediction of depression risk." (PMID 24312122, 2013). "It has been suggested that reduction in BDNF expression is a pathogenic factor common to Alzheimer’s disease and major depression." (PMID 23968401, 2013). "The association between BDNF and depression is also supported by animal studies in which infusion of recombinant BDNF exerted antidepressant effect." (PMID 23968401, 2013). "Brain-Derived Neurotrophic Factor (BDNF) is a neurotrophin that has been associated with some mental diseases, such as depression, Alzheimer’s disease and psychotic disorders." (PMID 23320462, 2013).
depression (continued). "Disruption in BDNF function has been implicated in the pathophysiology of several neuropsychological disorders such as anxiety, depression and schizophrenia." (PMID 23483949, 2013). "Why the present findings regarding the interaction between early life stress and the BDNF polymorphism in relation to depression differed from earlier studies isn’t certain, especially given the similarity of the procedures that were used." (PMID 23824678, 2013). "An amino acid substitution (valine to methionine) at codon 66 (Val66Met) is the most widely studied BDNF single-nucleotide polymorphism (SNP) in genetic association studies with depression." (PMID 24312122, 2013). "Compared with the healthy controls, patients with depression showed lower serum BDNF levels (via the enzyme-linked immunosorbent assays) and higher serum miR-132 and miR-182 levels (via the real-time PCR)." (PMID 23704927, 2013). "In the present study, we investigated the association of BDNF Val66Met polymorphism with depression in T2DM of Chinese Han subjects." (PMID 23968401, 2013). "Disturbances of brain derived neurotrophic factor (BDNF) signalling have been implicated in the evolution of depression, which likely arises, in part, as a result of diminished synaptic plasticity." (PMID 23824678, 2013). "Conversely, increased BDNF levels are associated with antidepressant treatment and alleviation of depression." (PMID 23691371, 2013). "Gender-specific effects have been reported for BDNF associations with depression and antidepressant treatment, as well as for NTRK2 with obsessive-compulsive disorder." (PMID 23750220, 2013). "In animals BDNF (Val66Met) predisposes to a depression-like behaviour after stress situations that recover normal values after the administration of antidepressants." (PMID 23862076, 2013). "Several studies have demonstrated a strong association between the expression of BDNF and the onset of depression." (PMID 23805233, 2013). "Lower expression of BDNF has been implicated in depression vulnerability such that the antidepressant effect seen with psychotrophic treatments is attributed to increasing BDNF levels, which theoretically restores hippocampal functioning." (PMID 24312122, 2013). "In this regard, child abuse and neglect among individuals with lifetime depression was associated with lower serum BDNF levels among carriers of the BDNF Val66Met polymorphism but not among those homozygous for the Val allele." (PMID 23675319, 2013). "Another focus of considerable interest and controversy in the field of gene-environment actions is the link between the serotonin transporter gene (5HTT, SLC6A4), stress and the BDNF gene in the risk of depression." (PMID 23503168, 2013). "Recent genetic association studies on neurotrophic factors investigated the brain-derived neurotrophic factor (BDNF) and the neurotrophin-3 receptor gene demonstrating association with depression, anxiety disorders or attention deficit hyperactivity disorder." (PMID 24324616, 2013). "Brain-derived neurotrophic factor (BDNF) has been implicated in the pathogenesis of major depression." (PMID 23968401, 2013). "A hierarchical linear regression was conducted to examine possible interactions between the childhood maltreatment subscales that were associated with depression and BDNF genotype." (PMID 23824678, 2013). "The functional Val66Met polymorphism of BDNF has been studied for its possible associations with depression, but reports were contradictory." (PMID 23968401, 2013). "Yet, we have demonstrated a significant association between the BDNF Val66Met polymorphism and depression within the T2DM group." (PMID 23968401, 2013). "CREB is one of the most studied phosphorylation-activated transcription factors linked to depression, and its activation plays a critical role in inducing a transcription-dependent program for gene expression such as BDNF." (PMID 24367510, 2013).